SIGMAR1 (sigma non-opioid intracellular receptor 1)
Diseases named in the same sentence as SIGMAR1 in open-access papers (continued):
Sharing a sentence is not in itself a finding about the gene and the disease.
ischemic heart disease (2 papers, 2022 to 2025). "Our results might provide a rationale to use Oxycodone, a multiple-opioid receptor agonist, as a new therapy to treat myocardial I/R injury via targeting SIGMAR1, suggesting that Oxycodone may be a promising complementary agent for clinically treating ischemic heart disease." (PMID 35412431, 2022).
Obesity (2 papers, 2016 to 2023). Accumulation of substantial excess body fat. "Naltrexone, an antagonist used in opioid overdose that also targets SIGMAR1, is being investigated for treating obesity." (PMID 37433298, 2023). "Furthermore, the increased in Npy and Sigmar1 gene expression further supported this obesity rat model." (PMID 27456968, 2016).
asthma (1 paper, 2023). "In this study, Sigmar1 level was decreased in OVA-induced asthma model, and activation of Sigmar1 by treatment with agonist (i.e., PRE084) improved asthmatic symptoms and reduced the levels of inflammatory cytokines in the airway." (PMID 37051024, 2023). "Consistent with our data, a previous study revealed that using Sigmar1 agonists can alleviate pulmonary inflammation in mouse OVA-induced asthma models." (PMID 37051024, 2023).
autoimmune disease (1 paper, 2018). A disorder resulting from loss of function or tissue destruction of an organ or multiple organs, arising from humoral or cellular immune responses of the individual to their own tissue constituents. "Moreover, given the effects of SIGMAR1 on epigenetic processes, the author suggests that Ayahuasca might be useful in the treatment of disorders in which the cellular memory is dysregulated, such as cancer and neurodegenerative and autoimmune diseases." (PMID 29674970, 2018).
diabetic retinopathy (1 paper, 2021). "Alterations in Sigmar1’s subcellular localization, expression, and signaling has been implicated in the progression of a wide range of diseases, such as neurodegenerative diseases, ischemic brain injury, cardiovascular diseases, diabetic retinopathy, cancer, and drug addiction." (PMID 34305655, 2021). "Sigmar1’s role in diabetic retinopathy was evident from two murine models of diabetic retinopathy, the streptozotocin-induced model and the Ins2Akita/+ mouse." (PMID 34305655, 2021).
distal myopathy (1 paper, 2021). Distal myopathy refers to a group of muscle diseases which share the clinical pattern of predominant weakness and atrophy beginning in the feet and/or hands. "Other allelic neurological disorders with the same gene associations are ataxia with oculomotor apraxia (SETX), HSP (ALS2, SPG11, ERLIN1, and DDHD1), JPLS (ALS2), dHMN (SIGMAR1), distal myopathy (GNE), and distal SMA (BICD2)." (PMID 34946884, 2021).
ganglion (1 paper, 2011). "In conclusion, from our in vivo experiments using Sigmar1−/− and WT mice, and optic nerve crush surgery to induce cell death, we defined a specific role for the σR1 in containing retinal ganglion cell degeneration." (PMID 21541278, 2011).
glomerular diseases (1 paper, 2025). "Therefore, Sigmar1 represents a promising therapeutic target for glomerular diseases such as nephrotic syndrome." (PMID 40005987, 2025). "Based on these findings, it is suggested that Sigmar1 may be a novel therapeutic target in the treatment of glomerular diseases, including nephritic syndromes." (PMID 40005987, 2025).
inflammatory bowel disease (1 paper, 2023). A spectrum of small and large bowel inflammatory diseases of unknown etiology. "Ligand-dependent studies showed the anti-inflammatory effects of Sigmar1 activation using its agonist, fluvoxamine, in inflammatory bowel disease." (PMID 37051024, 2023).
lung disease (1 paper, 2023). "In the present study, we used paraffin-fixed human (with no clinical record of lung disease) and mouse (Wt) lung tissue sections and performed immunohistochemical (IHC) staining using anti-Sigmar1 antibody." (PMID 37051024, 2023). "Using the same techniques, we also found Sigmar1 protein expression and localization in healthy human lungs that had no clinical history of lung disease." (PMID 37051024, 2023).
non-alcoholic fatty liver diseases (1 paper, 2016). "Similarly, obese individual with non-alcoholic fatty liver diseases was found to have up-regulation of opioid signalling including Sigmar1." (PMID 27456968, 2016).
oral cancer (1 paper, 2024). "In our study, we observed that SIGMAR1 overexpression was linked to unfavorable survival rates and was positively correlated with PD-L1 overexpression in human oral cancer samples." (PMID 39595926, 2024). "Our findings revealed that SIGMAR1 overexpression was associated with poor survival rates and positively correlated with PD-L1 overexpression in human oral cancer samples." (PMID 39595926, 2024). "Thus, survival data analysis was performed, and it revealed that high levels of SIGMAR1 (mRNA) are associated with a significantly worse prognosis for oral cancer patients (p = 0.033)." (PMID 39595926, 2024). "To examine the SIGMAR1 expression pattern in oral cancer, we used bulk RNA sequencing from TCGA data and our in-house cohort, which included 26 primary cases of OC samples." (PMID 39595926, 2024). "In this connection, further research is needed to elucidate the specific molecular mechanisms by which SIGMAR1 modulates PD-L1 expression and its implications for oral cancer progression and immunotherapy response." (PMID 39595926, 2024). "Collectively, our findings suggest that SIGMAR1 knockdown enhances the sensitivity of oral cancer cells to cisplatin by promoting apoptosis." (PMID 39595926, 2024). "All these findings suggest that SIGMAR1 may promote immune escape, possibly by upregulating PD-L1 expression in oral cancer cells." (PMID 39595926, 2024). "Thus, we selected these two different oral cancer cell lines with small hairpin RNAs (shRNAs) targeting SIGMAR1." (PMID 39595926, 2024). "Beyond suggesting potential immunomodulatory roles for SIGMAR1 in oral cancer, which are reflective of its poorer prognosis, our study provides novel evidence indicating that SIGMAR1 acts as a positive regulator of PD-L1 expression, thereby exacerbating chemoresistance in human oral cancer." (PMID 39595926, 2024). "Taken together, our results demonstrate that SIGMAR1 is overexpressed in oral cancer." (PMID 39595926, 2024). "Furthermore, SIGMAR1 inhibition led to a decrease in PD-L1 expression and sensitized oral cancer cells to cisplatin treatment by enhancing apoptosis." (PMID 39595926, 2024). "For instance, according to the heatmap, we could observe that in most human oral cancer samples, SIGMAR1 had a correlation profile with the PD-L1 expression values, in our cohort." (PMID 39595926, 2024). "Additionally, elucidating these cross-talks between SIGMAR1 and the tumor cellular microenvironment could significantly accelerate the identification of novel immunological biomarkers for oral cancer treatment." (PMID 39595926, 2024). "Thus, the HN12 cells shRNA_SIGMAR1 and the control group were used, and by flow cytometry, we also found that SIGMAR1 knockdown significantly decreased PD-L1 protein exposition at the surface of human oral cancer cell line compared to the control group (p < 0.001)." (PMID 39595926, 2024). "Nevertheless, the impact of SIGMAR1 on oral cancer is largely unknown." (PMID 39595926, 2024). "Overall, our study provides valuable insights into the role of SIGMAR1 in oral cancer pathogenesis and suggests that SIGMAR1-targeted interventions could represent a promising avenue for future clinical trials and therapeutic development in the field of oral cancer treatment." (PMID 39595926, 2024).
osteoporosis (1 paper, 2022). A condition of reduced bone mass, with decreased cortical thickness and a decrease in the number and size of the trabeculae of cancellous bone (but normal chemical composition), resulting in increased fracture incidence. "Under pathological conditions such as OVX‐induced bone loss, however, Sigmar1 gKO mice exhibited severe osteoporosis with a reduced BV/TV and trabecular number, suggesting that Sigmar1 exerted a protective effect on bone homeostasis, especially under pathological conditions." (PMID 35611810, 2022). "Micro‐CT revealed that Sigmar1 gKO‐OVX mice exhibited a severe osteoporosis phenotype with lower bone volume/tissue volume (BV/TV), trabecular number (Tb." (PMID 35611810, 2022). "Here, we investigated the role of Sigmar1 in osteoclastogenesis and found that Sigmar1 global knockout (gKO) mice exhibited severe osteoporosis after ovariectomy surgery (OVX) compared with WT littermates." (PMID 35611810, 2022). "Furthermore, the transfer of Sigmar1 gKO bone marrow cells into WT mice exacerbated the osteoporosis phenotype after the OVX surgery." (PMID 35611810, 2022). "In contrast, overexpression of Sigmar1 locally alleviated the osteoporosis phenotype." (PMID 35611810, 2022). "In conclusion, Sigmar1 is a negative regulator of osteoclastogenesis, and activation of Sigmar1 by dimemorfan may be a potential treatment for osteoporosis in clinical practice." (PMID 35611810, 2022). "The results presented herein demonstrated that Sigmar1 had a profound effect on bone homeostasis and could be a potential therapeutic target for treating osteoporosis." (PMID 35611810, 2022). "Here, we show that mice lacking Sigmar1 exhibited severe osteoporosis in an ovariectomized model." (PMID 35611810, 2022).
osteosarcoma (1 paper, 2025). A usually aggressive malignant bone-forming mesenchymal neoplasm, predominantly affecting adolescents and young adults. "In this study, five possible key targets of SS against osteosarcoma were finally identified: ATP1A1, CLK1, SIGMAR1, PYGM, and HSP90B1." (PMID 40831924, 2025). "Based on network pharmacology and transcriptomics, we identified ATP1A1, CLK1, SIGMAR1, PYGM, and HSP90B1 as the key targets of solasonine that influence the progression of osteosarcoma cells." (PMID 40831924, 2025). "It is speculated that ATP1A1, CLK1, SIGMAR1, PYGM, and HSP90B1 may serve as therapeutic targets for solasonine in the treatment of osteosarcoma." (PMID 40831924, 2025).
Prostate Tumors (1 paper, 2023). "Consistent with these experimental results, SIGMAR1 transcripts are strongly associated with lipid metabolism and ROS pathways in prostate tumors." (PMID 37874216, 2023).
pulmonary fibrosis (1 paper, 2023). Chronic progressive interstitial lung disorder characterized by the replacement of the lung tissue by connective tissue, leading to progressive dyspnea, respiratory failure, or right heart failure. "This indicates higher pulmonary inflammation resulting from Sigmar1 deficiency in mice, which was associated with increased pulmonary fibrosis." (PMID 37051024, 2023). "Overall, our data suggest that deletion of Sigmar1 leads to higher pulmonary inflammation and associated pulmonary fibrosis as an adaptive response." (PMID 37051024, 2023). "Our findings suggest that Sigmar1 deficiency leads to increased pulmonary inflammation, higher pulmonary fibrosis, alterations of the multilamellar body stuructures, and elevated levels of lung surfactant proteins." (PMID 37051024, 2023). "Sigmar1 deficiency can also cause increased pulmonary fibrosis, altered LB structures in type-II pneumocytes, and elevated protein levels of four surfactant precursor proteins, including SFTP-A, SFTP-B, SFTP-C, and SFTP-D." (PMID 37051024, 2023).
Ureteral obstruction (1 paper, 2024). Obstruction of the flow of urine through the ureter. "This study explored the role of Sigmar1 and its ligands in a CRS4 model induced by unilateral ureteral obstruction (UUO) in male and female C57BL/6 mice." (PMID 39200372, 2024).
uveal melanoma (1 paper, 2021). A melanoma derived from melanocytes of the uveal tract. "The effect of Sigmar1 on autophagy has also been reported by studies showing Sigmar1 ligands modulated the autophagic process in a dose-dependent manner uveal melanoma cells." (PMID 34305655, 2021).
cancer (33 papers, 2003 to 2026). A tumor composed of atypical neoplastic, often pleomorphic cells that invade other tissues. "Emerging evidence suggests that aberrant expression levels of Sigma1 (SIGMAR1, also known as sigma-1 receptor) have been implicated in the progression of various diseases, including cancer." (PMID 39595926, 2024). "SigmaR1 is either over- or under-expressed or found associating with distinct molecules in cancer, indicating the need for a more personalized approach to utilizing it clinically." (PMID 37444574, 2023). "SIGMAR1 plays an important role in the cellular functions of various tissues associated with the endocrine, immune, and nervous systems, in addition to cancer cells." (PMID 36435867, 2022). "Dysregulation of SIGMAR1 function is implicated in neuropsychiatric and neurodegenerative disorders, drug addiction, cancer, cardiovascular diseases, immune-related pathologies, stroke and neuropathic pain [Reviewed in]." (PMID 29674970, 2018). "Consequently, SigmaR1 has been implicated in a number of cancers and degenerative diseases and thus has been intensively pursued as a therapeutic target." (PMID 37444574, 2023). "For instance, the Sigma-1 receptor (SigmaR1), a chaperone protein enriched at MAMs, is overexpressed in several cancers, including breast and colorectal malignancies." (PMID 40724998, 2025). "In the context of tumorigenesis and cancer progression, SIGMAR1 has garnered attention due to its potential involvement in cancer biology." (PMID 39595926, 2024). "Conversely, targeting SIGMAR1 inhibits ferroptosis in cancer cells and mitigates cisplatin-induced acute kidney injury in mice through pharmacological means (using CGI1746 and BD1063) or genetic interventions." (PMID 38844964, 2024). "SIGMAR1 is upregulated in several cancers, such as lung, breast, glioblastoma, esophageal, pancreatic, prostate, and liver cancer." (PMID 38844964, 2024). "On the other hand, it was also reported that SIGMAR1 protein also plays an intriguing role in the immunomodulatory process (immunity and inflammation) and cancer progression." (PMID 39595926, 2024). "In this connection, our findings offer, for the first time, experimental evidence suggesting that SIGMAR1 modulators represent a novel class of therapeutic agents with the potential to revolutionize PD-L1/PD-1 blockade strategies in cancer immunotherapy." (PMID 39595926, 2024). "Overall, these studies illustrate the diversity of SigmaR1 functional interactions and differential influence on the different cancer cell types." (PMID 37444574, 2023). "Mechanistic studies into how SigmaR1 promotes cancer cell proliferation identified several signaling routes, at the heart of which are Ca2+ signaling and ER stress." (PMID 37444574, 2023). "Similar results were seen in lung cancer patients’ samples where Sigmar1 was secreted by tumor cells and increased the viability of squamous lung cancer cells, and correlated with increased survival of the cancer cells." (PMID 34305655, 2021). "Evidence proves that the loss of SIGMAR1 function can block the expression of GPX4 in vitro and in vivo to induce ferroptosis in cancer cells." (PMID 33867820, 2021). "Upregulated levels of Sigmar1 in different cancer cell lines drive cell migration, invasiveness, and promote cell survival by increasing calcium entry in the cells and regulating membrane electrical activity." (PMID 34305655, 2021). "On the other hand, in certain cancers, Sigmar1 may also promote tumor cell survival through autophagy regulation, thereby exacerbating disease progression." (PMID 42196470, 2026). "Recent studies have highlighted its functions in different types of cancers, indicating that SIGMAR1 might influence cancer cell survival, proliferation, and metastasis." (PMID 39595926, 2024). "Targeting SIGMAR1-mediated ferroptosis may present a novel strategy to shift cancer cells from a pro-survival to a pro-death state." (PMID 38844964, 2024).
cancer (continued). "Thus much exciting research remains ahead to decipher the exact role of SigmaR1 in cancer and developing potential treatments." (PMID 37444574, 2023). "Other SigmaR1 antagonists have also been studied for cancer cell inhibition." (PMID 37444574, 2023). "There were some disparate points of view between Sigmar1 and cancer." (PMID 35611810, 2022). "However, further studies are required to understand the exact mechanism and functions of Sigmar1 in different cancer cells." (PMID 34305655, 2021). "The physiological significance of elevated Sigma1 in tumors remains poorly understood, and how SIGMAR1 gene expression is regulated in cancer remains unclear." (PMID 31695608, 2019). "It is not surprising that over the past several years SigmaR1 has been studied as a possible target for treatment for many human illnesses, particularly Alzheimer’s and cancer." (PMID 37444574, 2023). "While SigmaR1 is not considered an oncoprotein, cancer cell lines require a functional SigmaR1 for proliferation and SigmaR1 inhibition has been found to prevent proliferation leading to apoptosis." (PMID 37444574, 2023). "Contrary to the results obtained from studies in cancer cells, knockout of Sigmar1 impaired mitochondrial clearance without altering the PINK1/Parkin signaling in mouse retinal explants and cultured cells (HEK-293, NSC34, and SH-SY5Ycell lines)." (PMID 34305655, 2021). "Importantly, this Ca2+ influx does not trigger apoptosis, suggesting that SigmaR1 contributes to cancer cell survival by finely tuning Ca2+ signaling without crossing the threshold for mitochondrial collapse." (PMID 40724998, 2025).
tumor (23 papers, 2003 to 2026). "GSEA revealed that SIGMAR1 mRNA is enriched in tumor tissue with elevated adipogenesis and ROS pathway–associated genes in both localized and metastatic prostate tumors, however, not in adjacent benign prostate tissue." (PMID 37874216, 2023). "As a result, the overexpression of SIGMAR1 was observed in tumors vs. adjacent non-tumor tissues in the TCGA data (p < 0.001) and confirmed in our in-house cohort study (p < 0.016)." (PMID 39595926, 2024). "Firstly, we evaluated the SIGMAR1 expression profiles in non-tumor oral keratinocytes spontaneously immortalized (NOK-SI) and in two human OC lines, SCC9 and HN12, by quantitative PCR and Western blot." (PMID 39595926, 2024). "The areas under the ROC curve were 0.8652 (p < 0.0001) and 0.6892 (p = 0.0029), respectively, suggesting a significantly high precision of SIGMAR1 in discriminating tumors from non-tumor tissues." (PMID 39595926, 2024). "Plasmid transfection was used to establish SIGMAR1-overexpressed and SIGMAR1-knockdown human granulosa-like tumor (KGN) cell and thapsigargin (TG) was used to induce ERS KGN cells." (PMID 32409627, 2020). "In this regard, we suggest that the overexpression of SIGMAR1 is probably a key contributor to chemoresistance and, consequently, tumor cell survival, due the fact that we also observed that the knockdown of SIGMAR1 decreased chemoresistance to cisplatin and increased apoptosis in human OC cells." (PMID 39595926, 2024). "Additionally, SIGMAR1 knockdown also reduces PD-L1 expression and mitigates cisplatin chemoresistance by promoting tumor apoptosis." (PMID 39595926, 2024). "In this regard, we hypothesize that SIGMAR1 may play significant roles in tumor-mediated immune escape, which is a crucial strategy for tumor survival, by inducing PD-L1 expression." (PMID 39595926, 2024). "Additionally, evidence suggests that SIGMAR1 may modulate the tumor microenvironment, influencing factors such as angiogenesis and immune evasion." (PMID 39595926, 2024). "However, interactions between SIGMAR1 and ion channels may change cellular behaviors in response to the microenvironment, leading to the unexpected consequence of tumor development." (PMID 36435867, 2022).